CD1D (CD1d molecule)
Diseases named in the same sentence as CD1D in open-access papers (continued):
Sharing a sentence is not in itself a finding about the gene and the disease.
colitis (23 papers, 2014 to 2025). Inflammation of the colon. "A previous study demonstrated that HFD feeding increases susceptibility of mice to DSS-induced colitis via a concurrent increase in CD1d-unrestricted NKT cells (mostly CD8+ and DN T cells) and a decrease in Tregs." (PMID 38274786, 2023). "We have previously shown that a deficiency of CD1d-restricted invariant natural killer T (iNKT) cells exacerbates dextran sulfate sodium (DSS)-induced colitis in Yeti mice that exhibit IFNγ-mediated hyper-inflammation." (PMID 36499642, 2022). "In conclusion, our results demonstrate that the upregulation of pathogenic Foxp3-CD25+CD4+ T cells induced by proinflammatory DCs is closely linked with increased susceptibility to DSS-induced colitis in iNKT cell-deficient Yeti/CD1d KO mice." (PMID 36499642, 2022). "Our results demonstrate that increases in the prevalence of Foxp3−CD25+CD4+ pathogenic effector T cells correlate with increased susceptibility to DSS-induced colitis in Yeti/CD1d KO mice." (PMID 36499642, 2022). "We found that Yeti mice display increased levels of ILC3s and that iNKT cell deficiency in Yeti/CD1d KO mice decreases levels of IL22-producing ILC3s during DSS-induced colitis." (PMID 33513946, 2021). "Taken together, these findings suggest that NK1.1+CD8+ T cells are pathogenic cells contributing to severe and spontaneous colitis in Yeti/CD1d KO mice." (PMID 30333822, 2018). "A murine model of oxazolone-induced colitis is associated with CD1d-dependent production of Th2 cytokines involved in mucosal inflammation." (PMID 24936795, 2014). "Furthermore, various CD1d-expressing cells (e.g., B cells, ILC3s, and macrophages) that can interact with iNKT cells also appear to play protective or pathogenic roles in colitis by producing cytokines (e.g., IL-22 and IL-10) via CD1d-intrinsic signaling." (PMID 38274786, 2023). "Additional studies have provided evidence that CD1d-dependent pathogenic iNKT cell activation by commensal-derived glycolipid Ags can be inhibited by competitive CD1d binding with globotriaosylceramide and α-lactosylceramide during iNKT cell-mediated Oxa-induced colitis." (PMID 38274786, 2023). "Therefore, to investigate whether the downregulation of Treg cells in Yeti/CD1d KO mice during DSS-induced colitis might be caused by altered DC functions, we evaluated the effects of DCs on Treg cell differentiation in these mice." (PMID 36499642, 2022). "Early studies noted upregulated CD1d expression in splenic IL-10+ B cell subsets in murine models, which correlated with colitis." (PMID 39346706, 2024). "In the murine model of oxazolone-induced colitis, CD1d expressed on bone marrow-derived cells elicits pathogenic effects by mediating activation of NKT cells, while CD1d expression by IECs leads to protection mediated by IL-10 production." (PMID 38579449, 2024). "In the mouse model of oxazolone-induced colitis, NKT cells accumulate in the gut, while there is protection from disease in NKT cell-deficient mice or WT mice pre-treated with anti-CD1d blocking antibodies." (PMID 39580798, 2024). "The increased production of TNFα and IFN-γ by CD1d-independent NK1.1+CD8+ T cell populations can facilitate the pathophysiology of colitis." (PMID 39201260, 2024). "Conversely, specific deletion of CD1d in IECs, results in reduced IL-10 production and severe oxazolone-mediated colitis." (PMID 38579449, 2024). "Further, CD1d+ Bregs suppressed intestinal inflammation in mice with colitis, in an IL-10-dependent manner." (PMID 39346706, 2024). "In DSS-induced colitis, WT B6 mice that received B6 CD1d KO-derived cecal contents show increased sensitivity to colitis compared with control WT B6 mice injected orally with WT B6-derived cecal contents." (PMID 38274786, 2023). "We have previously reported that CD1d-independent CD8+ NKT cells are critical effectors that exacerbate DSS-induced colitis in Yeti mice characterized by enhanced stability of IFN-γ mRNA transcripts." (PMID 38274786, 2023).
colitis (continued). "In contrast, through cooperation with Tregs, iNKT cells are required to control CD1d-independent CD8+ NKT cell-mediated pathogenesis during DSS-induced colitis." (PMID 38274786, 2023). "Therefore, we decided to examine whether MLN CD25+CD4+ T cells from DSS-treated Yeti/CD1d KO mice (mostly Foxp3− populations) can increase susceptibility to DSS-induced colitis compared to CD25+CD4+ T cells (primarily Foxp3+ populations) from DSS-treated CD1d KO mice." (PMID 36499642, 2022). "Our previous study demonstrated that CD1d-dependent iNKT cells play a significant role in controlling DSS-induced colitis in Yeti mice." (PMID 33513946, 2021). "From this set of experiments, we conclude that CD1d-dependent iNKT cells from Yeti mice play a significant role in controlling DSS-induced colitis." (PMID 33513946, 2021). "We have previously demonstrated that CD1d-dependent iNKT cells play a significant role in controlling DSS-induced colitis in C57BL/6 (B6) background Yeti mice with dysregulated IFNγ-mediated autoinflammation." (PMID 33513946, 2021). "We recently reported that NK1.1+CD8+ (CD1d-independent) T cells are critical effector cells that exacerbate DSS-induced colitis in Yeti mice." (PMID 33513946, 2021). "24αβ cells suppressed type I diabetes onset in mice, but exacerbated colitis when CD1d was overexpressed in 24αβ CD1dTg+ mice." (PMID 33312179, 2020). "On the other hand, ERCs increased the production of IL-10 and the proportion of CD1d+CD5+ Bregs from colitis mice, an important source of IL-10." (PMID 29784012, 2018). "Antibody-mediated inhibition of CD1d-dependent antigen presentation resulted in a significant increase in total leukocyte numbers in the colon at day 7 of DSS-induced colitis." (PMID 29867976, 2018). "To examine the direct effect of Bregs in ERC-based therapy, we isolated CD1d+CD5+ Bregs from the spleen of ERC-treated colitis mice to perform adoptive transfer, which is an important IL-10 source." (PMID 29784012, 2018). "We further showed that iNKT cells and Treg cells contribute to colitis protection, whereas expansion of CD1d-independent NK1.1+CD8+ T cells contributes to colitis pathogenesis." (PMID 30333822, 2018). "On the other hand, colitis in CD1d KO mice was only slightly increased compared with WT mice, suggesting that lack of iNKT cells by itself is not sufficient to induce exacerbated colitis." (PMID 30333822, 2018). "In the TCRα−/− spontaneous colitis model, B cells protected the colon from severe inflammation by generating CD1d upregulated Bregs capable of producing interleukin (IL)-10." (PMID 29784012, 2018). "Upon DSS-induced colitis, when compared with CD1d KO mice, WT mice that received NK1.1+CD8+ T cells displayed significantly increased frequency of Treg cells in the LP." (PMID 30333822, 2018). "Upon DSS-induced colitis, when compared with CD1d KO mice, WT mice that received NK1.1+CD8+ T cells showed significantly decreased frequency of Th1 and Th17 cells in the LP." (PMID 30333822, 2018). "Taken together, these results indicate that CD1d-dependent iNKT cells play a major role in controlling DSS-induced colitis in Yeti mice." (PMID 30333822, 2018). "To examine the role of type II NKT cells in colitis under choline-deficient conditions, we assessed the severity of DSS-induced colitis in type I NKT cell-deficient (Jα18-/-) or type I and type II NKT cell-deficient (CD1d-/-) mice fed the MCD or CTR diets." (PMID 28095507, 2017). "When CD1d was simultaneously knocked out, the symptoms of colitis became more severe, thereby suggesting that the B-cell subset can regulate inflammation in the colitis models." (PMID 27515534, 2016). "This is consistent with earlier studies demonstrating that systemic α-GalCer improved outcomes in DSS colitis in wildtype mice, but not in global CD1d deficient mice." (PMID 41041542, 2025).
colitis (continued). "Deletion of CD1d on goblet cells reversed the protective effects of EGFRi treatment on DSS colitis, including colon shortening and histology scores, consistent with the protective effect of EGFRi being mediated through CD1d expression by goblet cells and colonic iNKT cell expansion." (PMID 41041542, 2025). "Also, CD1d expression is altered in the intestines of patients with inflammatory bowel disease, and in the model of oxazolone-induced colitis, NKT cells are key regulators of inflammation." (PMID 39580798, 2024). "Accordingly, it has been shown that macrophage-specific CD1d outside-in signalling is detrimental for DSS-induced colitis progression, as CD1d intracellular signalling inhibits NLRP3 inflammasome, which in turn regulates gut-blood barrier integrity and intestinal homeostasis." (PMID 38579449, 2024). "The factors underlying these inconsistencies remain unclear, but alterations in the microbiota of CD1d-KO strains have been proposed to have a critical influence in the outcome of DSS colitis." (PMID 38579449, 2024). "Since IL-10-producing B cells (B10) suppress experimental arthritis in a CD1d-dependent manner, it will be interesting to investigate whether iNKT cells cross-talk with B10 cells to regulate colitis." (PMID 38274786, 2023). "Glycolipid Ags derived from the intestinal microbe B. fragilis (called GSL-Bf717 or BfaGCs) inhibit iNKT cell activation through competitive binding of their sphinganine branches with CD1d, resulting in protection against oxazolone (Oxa)-induced colitis, an experimental model mimicking UC." (PMID 38274786, 2023). "Furthermore, an increase in particular segmented filamentous bacteria and a decrease in Akkermansia muciniphila (A. muciniphila) closely correlates with increased colitis sensitivity in WT B6 mice that received B6 CD1d KO-derived cecal contents." (PMID 38274786, 2023). "IL-10 promotes the proliferation and differentiation of B cells into IgA-secreting plasma cells and also acts as an anti-inflammatory cytokine to inhibit NKT cell-mediated colitis and protect intestinal mucosa by regulating the expression of CD1d in intestinal epithelial cells." (PMID 36425118, 2022). "In a spontaneous model of colitis, B cells isolated from CD1d-deficient mice failed to suppress the disease when transferred to TCRα−/− mice, confirming the importance of CD1d in the regulatory function of B cells." (PMID 29449556, 2018). "However, they also showed that CS exposure increased mRNA expression of inflammatory cytokines including TNF, IFN-γ, IL-17, and IL-21 in Ja18−/− mice and escalated clinical symptoms of DSS-induced colitis in CD1d−/− mice." (PMID 29163466, 2017). "Type II NKT cells exposed in vivo to low levels of CD1d expression may fail to contribute to the development of colitis in mice." (PMID 28095507, 2017). "Thus, we examined the expression of memory markers (CD44 and Eomes), NK cell receptors (NKG2D and Ly49a), cytolytic molecules (FasL and Perforin), and pro-inflammatory cytokines (IFNγ and TNFα) in MLN-derived NK1.1+CD8+ T cells from Yeti/CD1d KO mice during DSS-induced colitis." (PMID 30333822, 2018). "Moreover, adoptive transfer of lamina propria cells from Jα18-/- mice, but not from CD1d-/- mice, aggravated colitis in Jα18-/- mice with choline deficiency." (PMID 28095507, 2017). "The improved outcome is at least in part attributable to iNKT cells, as deletion of CD1d on goblet cells, which inhibited colonic iNKT cell expansion in response to GAP induction, abrogated the protective effect of GAP induction on DSS colitis." (PMID 41041542, 2025). "Therefore, to examine whether MLN DCs from Yeti/CD1d KO mice show proinflammatory phenotypes during DSS-induced colitis, we compared proinflammatory cytokine production (i.e., IL12, TNFα, and IL6) by both splenic DCs and MLN DCs from WT, Yeti, CD1d KO, and Yeti/CD1d KO mice during DSS treatment." (PMID 36499642, 2022).
colitis (continued). "Furthermore, one study demonstrated that IECs produce high amounts of IL-10 via CD1d engagement-induced STAT3 activation, suppressing Oxa-induced iNKT cell-mediated colitis." (PMID 38274786, 2023). "CD1d independent NK1.1+CD8+ T cells produced high levels of IFN-γ and TNFα, contributing to colitis pathogenesis, and suggested that DCs and macrophages might be responsible for increasing NK1.1+CD8+ T cells through IL-15." (PMID 35741032, 2022). "In a TCR-aKO model of spontaneous colitis, it was also shown that MLN CD1d+IgM-producing B-cells could suppress intestinal inflammation through the production of IL-10." (PMID 35163775, 2022). "Moreover, it is worth noting that CD1d crosslinking in ILC3s induces secretion of IL-22 which is known to support epithelial barrier function and has been shown to be protective in DSS-induced colitis." (PMID 38579449, 2024). "Thus, it will be important to explore how CD1d-intrinsic signaling modulates the function of NKT cells and whether such interactions contribute to colitis development." (PMID 38274786, 2023). "The frequencies of Th1 and Th17 cells in Yeti/CD1d KO mice were two- to three-fold greater in the MLN and LP, but not in the spleen, than those from Yeti mice, indicating that the protective role of iNKT cells in colitis was largely restricted to the MLN and LP." (PMID 30333822, 2018). "In DSS-induced colitis, the number of NK1.1+CD8+ T cells in the spleen and MLN from Yeti mice was expanded approximately 6-fold compared with WT mice, and the number of NK1.1+CD8+ T cells from Yeti/CD1d KO mice was increased eight-fold compared with CD1d KO mice." (PMID 30333822, 2018). "We also found that the MCD diet improved colitis in Jα18-/- mice but not in CD1d-/- mice." (PMID 28095507, 2017). "Moreover, we also compared the development of colitis in MCD or CTR CD1d-/- mice to determine whether the effect remains without type II NKT cells." (PMID 28095507, 2017). "The suppressive effects of B cells in colitis have been demonstrated by TCR-α−/− × Igμ−/− mice lacking B cells spontaneously developing more severe colitis than TCR-α−/− mice and adoptive transfer of IL-10-producing CD1d+CD5+ Bregs inhibiting the DSS-induced intestinal injury in a mouse model." (PMID 29784012, 2018). "Additionally, CD1d-independent NK1.1+ T cells have been identified in the intestinal tissues of CD1d knockout (KO) mice, but their potential contribution to the pathogenesis of colitis has not been explored." (PMID 30333822, 2018).
lymphoma (22 papers, 2010 to 2026). A malignant (clonal) proliferation of B- lymphocytes or T- lymphocytes which involves the lymph nodes, bone marrow and/or extranodal sites. "Underscoring this point, we previously showed that CAR-iNKT cells are more effective against CD1d-expressing lymphoma than their CAR T-cell counterparts, and KMT2Ar ProB ALL has been previously reported to express CD1d." (PMID 40898981, 2026). "Cancer cells of hematologic malignancy, such as AML and lymphoma, thus also express CD1d and can activate iNKT cells if they present iNKT ligand such as α-galactosylceramide (αGC) onto CD1d." (PMID 39301248, 2024). "For example, the anti-lymphoma function of CAR-NKT cells can be improved by inducing more translation and expression of CD1d on lymphoma cells and CLL-B cells, which is mediated by all-trans retinoic acid (ATRA)." (PMID 37158883, 2023). "Higher levels of CD1d on lymphoma cells were also correlated with reduced IFN-γ production by remaining iNKT cells." (PMID 29375569, 2017). "It was found that the addition of α-GalCer to NKT cell/lymphoma co-cultures resulted in the induction of cytokine production by NKT cells, even when lymphoma CD1d expression was undetectable by flow cytometry." (PMID 24955247, 2014). "Therefore, we investigated the function of iNKT in a second immunocompetent system, using a syngeneic lymphoma model that induces CD1d positive MDSCs in vivo." (PMID 35962843, 2023). "In particular, our data suggests that for Vδ1 lymphomas the antigen may be a lipid presented by CD1d." (PMID 32286303, 2020). "Aberrant S1P signal transduction and intracellular transit in B cell lymphomas may potentially result in the deregulation of CD1d-mediated activation NKT cells by lymphomas, contributing to the NKT-cell activation deficit described here." (PMID 32326225, 2020). "In particular, iNKT cells, that are CD1d-restricted cells, can induce cell death of chronic lymphocytic leukemia cells after stimulation with alphaGalCer, and can trigger secondary anti-lymphoma response in murine models of lymphoma." (PMID 24302998, 2013). "Moreover, rat CD1d and mouse CD1d1 expressed by human lymphoma cells (Raji) as transgenes had the same molecular size as CD1d expressed by rat and mouse thymocytes." (PMID 20927351, 2010). "Thus, we propose that Arid5a-IL-6 interactions in CD1d– (IL-5R–) B1 B cells may have promoted the development of lymphoma, different from NKT2 connecting CD1d+B1 B cells." (PMID 36050343, 2022). "Additionally, CD19-specific NKT cells were found to be more effective than CD19-targeting CAR-T cells against CD1d-expressing lymphomas in vitro and in vivo, suggesting CAR-NKTs can provide unique advantages in treating lymphomas and other CD1d-expressing tumors." (PMID 32244520, 2020). "In anti-thymocyte/Thy-1 autoreactive μκ transgenic (ATAμκ Tg) Pla2g2a+ BALB/c background C.B17 mice generated NKT2 cells that continuously control CD1d+ B1 B cells through old aging and lost CD1d in B1 B cells generating strong B1 ATA B cell leukemia/lymphoma." (PMID 36050343, 2022). "When iNKT cells are engineered with a CD19 CAR, they show strong anti-lymphoma properties by targeting both CD19 and CD1d expressed on lymphoma cells." (PMID 34885176, 2021). "Regardless, human CD19 CAR NKT cells against lymphoma, and GD2 CAR NKT cells against neuroblastoma, have demonstrated preclinical efficacy, with CD19 CAR NKT cells exerting anti-lymphoma activity through both the CAR and the invariant TCR interaction with CD1d." (PMID 36876006, 2023). "In contrast, αGC as a free drug was unable to activate iNKT cell clones in the absence of APCs and required the presence of CD1d-expressing cells such as the human lymphoma C1R transfected with CD1d." (PMID 23242316, 2013). "A comparison of the tumor growth phenotypes in CD1d−/− and Jalpha18−/− mice suggested that type II NKT cells may inhibit lymphoma growth in the absence of iNKT cells." (PMID 22880059, 2012).